EREG (epiregulin)
Description:
Ligand of the EGF receptor/EGFR and ERBB4. Stimulates EGFR and ERBB4 tyrosine phosphorylation. Contributes to inflammation, wound healing, tissue repair, and oocyte maturation by regulating angiogenesis and vascular remodeling and by stimulating cell proliferation.
Synonyms: EPR; ER; Ep
Tractability: Antibody: a drug acting on it is in phase 2 or 3 trials; UniProt places it where antibodies can reach, with high confidence; its Gene Ontology location is reachable by antibodies, with high confidence; UniProt predicts a signal peptide or a membrane-spanning region.
Gene: Protein-coding gene on chromosome 4 (74,365,145 to 74,388,749, forward strand). Ensembl gene ENSG00000124882.
Subcellular location: Secreted, extracellular space (Epiregulin); Cell membrane (Proepiregulin)
Subcellular location (Human Protein Atlas): Vesicles; Cytosol; Predicted to be secreted
Pathways (Reactome):
Signal Transduction: Downregulation of ERBB2 signaling; EGFR downregulation; EGFR interacts with phospholipase C-gamma; ERBB2 Activates PTK6 Signaling; ERBB2 Regulates Cell Motility; Estrogen-dependent nuclear events downstream of ESR-membrane signaling; Extra-nuclear estrogen signaling; GAB1 signalosome; GRB2 events in EGFR signaling; GRB2 events in ERBB2 signaling; Nuclear signaling by ERBB4; PI3K events in ERBB2 signaling; PI3K events in ERBB4 signaling; PI5P, PP2A and IER3 Regulate PI3K/AKT Signaling; PIP3 activates AKT signaling; RAF/MAP kinase cascade; SHC1 events in EGFR signaling; SHC1 events in ERBB2 signaling; SHC1 events in ERBB4 signaling; Signaling by EGFR; Signaling by ERBB2; Signaling by ERBB4
Disease: Constitutive Signaling by Aberrant PI3K in Cancer; Inhibition of Signaling by Overexpressed EGFR; Signaling by ERBB2 KD Mutants; Signaling by ERBB2 TMD/JMD mutants
Vesicle-mediated transport: Cargo recognition for clathrin-mediated endocytosis; Clathrin-mediated endocytosis
Gene Ontology:
Molecular function: protein binding; receptor ligand activity; transmembrane receptor protein tyrosine kinase activator activity; epidermal growth factor receptor binding; growth factor activity
Biological process: cell-cell signaling; cytokine-mediated signaling pathway; epidermal growth factor receptor signaling pathway; ERBB2-EGFR signaling pathway; ERBB2-ERBB4 signaling pathway; ERBB4-ERBB4 signaling pathway; keratinocyte proliferation; mRNA transcription; negative regulation of DNA-templated transcription; negative regulation of smooth muscle cell differentiation; positive regulation of cell population proliferation; positive regulation of cytokine production; positive regulation of DNA replication; positive regulation of fibroblast proliferation; positive regulation of phosphorylation; positive regulation of protein kinase activity; anatomical structure morphogenesis; animal organ morphogenesis; female meiotic nuclear division; keratinocyte differentiation; luteinizing hormone signaling pathway; negative regulation of cell population proliferation; negative regulation of epithelial cell proliferation; oocyte maturation; ovarian cumulus expansion; and 10 more
Cellular component: extracellular region; clathrin-coated endocytic vesicle membrane; plasma membrane
Genetic constraint (gnomAD): Loss-of-function variants: 13 observed, 10.31 expected, observed/expected ratio (o/e) 1.26, 90% interval 0.81 to 1.84. The upper end of that interval is the gene's LOEUF score, 1.84, which puts it in group 6 of 6, group 1 being the genes least tolerant of losing a copy. Missense variants: 124 observed, 113.69 expected, observed/expected ratio (o/e) 1.09, 90% interval 0.94 to 1.27. Synonymous variants: 47 observed, 41.11 expected, observed/expected ratio (o/e) 1.14, 90% interval 0.9 to 1.46.
Homologues: Orthologues: chimpanzee EREG (99% identical), macaque EREG (97% identical), pig EREG (86% identical), rabbit EREG (86% identical), dog EREG (79% identical), guinea pig EREG (79% identical), mouse Ereg (78% identical), rat Ereg (77% identical), tropical clawed frog ereg (38% identical). Paralogues in human: EPGN (26% identical), BTC (22% identical), TGFA (18% identical), AREG (18% identical), HBEGF (15% identical).
Diseases named in the same sentence as EREG in open-access papers:
EREG is named in the same sentence as 132 diseases in open-access papers, as found by Europe PMC text mining. Sharing a sentence is not in itself a finding about the gene and the disease. The quoted sentences say what the papers report.
colorectal cancer (41 papers, 2009 to 2025). A primary or metastatic malignant neoplasm that affects the colon or rectum. "In clinical application, high EREG expression was associated with a longer OS compared with low EREG expression in RAS wild-type colorectal cancer patients receiving anti-EGFR antibody therapies." (PMID 38398101, 2024). "One study suggested that low EREG expression is associated with better overall survival in colorectal cancer patients." (PMID 31217031, 2019). "Our study confirms published data on the prognostic/predictive significance of BRAF, KRAS mutations and on the tumour expression of AREG, EREG mRNA in cetuximab-treated patients with colorectal cancer." (PMID 23374602, 2013). "Other potential biomarkers of cetuximab activity in colorectal cancer include EGFR ligands (epiregulin and amphiregulin) and polymorphisms in EGFR, EGF, and Fc fragment of IgG receptor." (PMID 19127259, 2009). "Recently, several studies have reported that AREG (and EREG) expression was associated with the likelihood of liver metastasis in colorectal cancer, and suggested that it might play an important role in the development of liver metastasis." (PMID 22409860, 2012). "However, in colorectal cancer patients receiving cetuximab, high gene expression of epiregulin and amphiregulin in tumour was associated with better outcome." (PMID 19127259, 2009). "In colorectal cancer, EREG is regulated by methylation, and its expression is associated with CIMP status and primary tumor location." (PMID 39883700, 2025). "As the ligand of EGFR, EREG is commonly upregulated in cancer types, such as non-small cell lung cancer, breast cancer, gastric cancer, head and neck cancer, ovarian cancer, colorectal cancer, brain cancer, and bladder cancer." (PMID 37020674, 2023). "We found that TSGs (e.g., DKK1 and GAS5) in colorectal cancer with hypermethylated promotors were re-activated and two oncogenes (i.e., EREG and MALAT1) were down-regulated upon 5-AZA-CdR treatment." (PMID 36882403, 2023). "Upregulation of EREG in colorectal cancer tissues correlates with depth of tumor invasion, distant metastases, and poor prognosis." (PMID 37623781, 2023). "Expression of the epidermal growth factor ligands amphiregulin (AREG) and epiregulin (EREG) is positively correlated with a response to EGFR-targeted therapies in colorectal cancer." (PMID 31370270, 2019). "Recently, an intragenic methylation of AREG and EREG genes has been shown to be inversely correlated with their expression in both colorectal cancer cells and human colorectal cancer samples." (PMID 31370270, 2019). "The CO-17 study, which compared treatment with cetuximab and best supportive care (BSC) to BSC alone in patients with metastatic EGFR-positive colorectal cancer, revealed that EREG expression levels were positively correlated with cetuximab treatment efficacy." (PMID 26884344, 2017). "Epidermal growth factor receptor (EGFR) and its ligands amphiregulin (AREG) and epiregulin (EREG) play a central role in the development of colorectal cancer, but the prognostic values of AREG and EREG are controversial." (PMID 27344184, 2016). "Overexpression of epiregulin has already been reported in psoriatic epidermis, and a high tissue level of epiregulin is a predictor of a poor prognosis in patients with colorectal carcinoma." (PMID 23826119, 2013). "The purpose of this study is to determine the correlation of AREG and EREG expression between primary colorectal cancer and corresponding liver metastases." (PMID 22409860, 2012). "In this study, modest correlations of AREG and EREG relative mRNA expression were observed between primary colorectal cancer and corresponding liver metastases." (PMID 22409860, 2012). "Recently, two large studies on AREG and EREG expression in patients with colorectal cancer who received Cetuximab were published." (PMID 22409860, 2012).
colorectal cancer (continued). "Moreover, high tumor EREG expression predicts a favorable response to cetuximab in KRAS wild-type colorectal cancer, suggesting its utility as a companion biomarker." (PMID 41175573, 2025). "High levels of EREG expression in colorectal cancer (CRC) associate with better therapeutic outcomes, while EREG overexpression in non-small cell lung cancer may be a therapeutic target for EGFR-TKI." (PMID 38334792, 2024). "Additionally, POLR1D has been observed to influence the expression of VEGF-α and EREG, resulting in acquired resistance to bevacizumab in colorectal cancer." (PMID 38256104, 2024). "EREG is overexpressed in many types of cancer including colorectal cancer." (PMID 36874096, 2023). "Similarly, in gastric cancer and colorectal cancer, upregulated EREG also predicts the shorter survival of patients." (PMID 37020674, 2023). "In colorectal cancer, EREG serves as a biomarker of anti-EGFR therapy." (PMID 32596278, 2020). "While it has been proposed as a biomarker for monitoring responses to cetuximab in colorectal cancer, it is unclear whether there is a function for EREG specifically in the context of radiation responses in these tumors." (PMID 29720118, 2018). "In the case of cetuximab treatment of colorectal cancer, which targets another receptor of the ERBB-family (the epidermal growth factor receptor) the expression of receptor ligands (i.e. amphiregulin and epiregulin), as well KRAS mutation, predict treatment response." (PMID 22014070, 2011). "Constitutive expression of EREG is low in normal tissues but elevated in various cancer types, such as non-small cell lung cancer, breast cancer, gastric cancer, head and neck cancer, ovarian cancer, colorectal cancer, brain cancer, bladder cancer, and is thought to promote tumor progression." (PMID 37623781, 2023). "The EREG (epiregulin) gene can function as a ligand of EGFR (epidermal growth factor receptor), as well as a ligand of most members of the ERBB (v-erb-b2 oncogene homolog) family of tyrosine-kinase receptors and is known to be associated to diseases like colorectal cancer, and hypopharynx cancer." (PMID 29233967, 2017). "Therefore, our findings indicate that elevated YBX1 protein levels may promote colorectal cancer progression by recognizing and stabilizing oncogenic transcripts such as EREG, MAFG, and GAS6, thereby activating downstream signaling pathways involved in tumorigenesis." (PMID 40819060, 2025). "It was initially reported that EREG expression and the efficacy of the EGFR inhibitors are closely correlated in colorectal cancer." (PMID 32929368, 2020). "EREG plays a carcinogenic role by binding to EGFR in various human tumors, such as colorectal cancer, nonsmall cell lung cancer, and gliomas." (PMID 33456463, 2020). "High EREG and AREG expressions are a predictive marker for panitumumab therapy benefit on PFS in RAS wild-type advanced colorectal cancer patients." (PMID 32587640, 2020). "We further narrowed this list by filtering genes with a known role in human colorectal cancer and/or cellular response to ionizing radiation that resulted in a group of four genes -CAB39, EMSY, EREG, and MEX3C." (PMID 29720118, 2018). "Amphiregulin (AREG) and epiregulin (EREG), which are ligands of EGFR, are overexpressed in colorectal cancer at both the mRNA and protein levels." (PMID 27344184, 2016). "Amphiregulin (AREG) and Epiregulin (EREG), ligands of EGFR, are reported to be predictive biomarkers of colorectal cancer patients treated with Cetuximab, an anti-EGFR antibody." (PMID 22409860, 2012). "Intriguingly, unlike EGF and EREG, NRG1 failed to support the growth of pre-tumorigenic intestinal organoids lacking the tumor suppressor Apc, commonly mutated in human colorectal cancer (CRC)." (PMID 36912192, 2023). "EGFR and its ligands EREG and AREG are commonly overexpressed in colorectal cancer." (PMID 37974093, 2023).
colorectal cancer (continued). "It was reported that in the setting of pretreated advanced colorectal cancer (ACRC), patients with high EREG gene expression may benefit from cetuximab therapy." (PMID 32906628, 2020). "Using a bioinformatics approach, we narrowed down the targets of miR-451a to a group of 14 genes, which was further filtered to 4 genes –CAB39, EMSY, EREG and MEX3C based on either a known role in colorectal cancer or radiation responsiveness in other cancer types." (PMID 29720118, 2018). "Although several previous reports demonstrated the association between EREG (and/or AREG) expression and survival time in KRAS wild-type patients who had received Cetuximab, no previous paper reported the association in colorectal cancer patients who had never received anti-EGFR antibody." (PMID 22409860, 2012).
breast cancer (38 papers, 2013 to 2025). A primary or metastatic malignant neoplasm involving the breast. "BCAR1/p130Cas drives treatment resistance in breast cancer and other malignancies, but EREG expression is associated with suitable outcomes, especially in left-sided mCRC." (PMID 34830244, 2021). "EREG is closely associated with the progression of various tumors, including gynecological cancer, rectal cancer, lung adenocarcinoma, breast cancer, and lung squamous cell carcinoma." (PMID 33613623, 2020). "Previous studies found detectable levels of EREG mRNA in up to 45.5 % of breast cancer and EREG has been linked to pulmonary metastasis in experimental studies." (PMID 26215578, 2015). "Finally, we demonstrate that loss of EREG expression in transformed breast cancer cells leads to reduced tumor growth in vivo, which is associated with increased tumor cell apoptosis." (PMID 26215578, 2015). "In breast cancer, EREG is part of a multi-gene co-regulation system together with lnc021545 and miR-330-3p that affects the metastasis of breast-cancer." (PMID 39654143, 2024). "Tamoxifen increases EREG gene expression by inhibiting miR-186-3p, which is essential for tamoxifen-resistant breast cancer cells to induce glycolysis." (PMID 37204526, 2023). "Previous studies revealed that the overexpressed EREG closely correlates with many cancers, including prostate cancer, colon cancer, breast cancer, and bladder cancer." (PMID 35422861, 2022). "In breast cancer cells, through modulating EREG signaling, miR-186-3p induced aerobic glycolysis and tamoxifen resistance." (PMID 34804161, 2021). "In breast cancer, miR-186-3p overexpression markedly restrains EREG expression, thus inhibiting the drug resistance and glycolysis of cancer cells." (PMID 34193018, 2021). "In line with this, the overexpression of this receptor enhances the osteolytic potential of intratibially injected breast cancer cells through epiregulin-mediated osteoprotegerin downregulation." (PMID 33113952, 2020). "The present study shows that EREG mRNA levels are inversely correlated with the mammary tumor microvascular density." (PMID 32674321, 2020). "LINC00885 silencing in breast cancer lines overexpressing this lncRNA leads to downregulation of proliferation related transcripts such as EREG, CMYC, CCND1 and to significant decrease in cell migration and motility." (PMID 33049922, 2020). "Previous studies have shown the Epiregulin (EGFR) ligands have the effect of stabilizing receptors, affecting breast cancer cells associated with differentiation function." (PMID 31001929, 2019). "Matrix metalloproteinase-1 (MMP-1), matrix metalloproteinase-2 (MMP-2), cyclooxygenase-2 (COX-2), and epiregulin (EREG) synergistically promote breast carcinoma intravasation by stimulating neoangiogenesis and leaky blood vessel formation." (PMID 31817450, 2019). "To conclude, our data revealed an important role for the CaSR-epiregulin axis on metastatic breast cancer cells osteolytic potential." (PMID 28915604, 2017). "At site of bone resorption, the activation by Ca2+ of the CaSR expressed by metastatic breast cancer cells favors epiregulin synthesis and secretion, which in turn acts on osteoblastic cells to reduce OPG synthesis." (PMID 28915604, 2017). "Secondly, several genes important to the development or aggressiveness of breast cancer including EREG, which is involved in ER/HER2 status, are located within this band." (PMID 26264669, 2016). "qRT-PCR was performed to assess expression levels of EREG, AREG, EGF, HB-EGF and TGFα, all of which have been implicated in breast cancer." (PMID 26215578, 2015). "In the studies described here, we demonstrate that EREG expression is increased in early stage breast cancer lesions." (PMID 26215578, 2015). "Several EGF ligands have been implicated in breast cancer, including EGF, epiregulin (EREG), amphiregulin (AREG), heparin-bound EGF (HB-EGF) and transforming growth factor alpha (TGFα)." (PMID 26215578, 2015).